MIR301B (microRNA 301b)
Synonyms: hsa-mir-301b; MIRN301B; mir-301b
Gene: MicroRNA gene on chromosome 22 (21,652,981 to 21,653,058, forward strand). Ensembl gene ENSG00000212102.
Homologues: Orthologues: chimpanzee ptr-mir-301b (100% identical), macaque mml-mir-301b (99% identical), dog MIR301B (95% identical), rat Mir301b (88% identical), guinea pig MIR301B (86% identical), mouse Mir301b (83% identical), mouse Mir130b (59% identical), rat Mir130b (59% identical), tropical clawed frog xtr-mir-130b (56% identical). Paralogues in human: MIR301A (68% identical), MIR130A (53% identical).